ENSG00000288698 (novel protein)
Gene: Protein-coding gene on chromosome 3 (179,604,807 to 179,784,179, forward strand). Ensembl gene ENSG00000288698.
Genetic constraint (gnomAD): Missense variants: 96 observed, 81 expected, observed/expected ratio (o/e) 1.19, 90% interval 1 to 1.4. Synonymous variants: 41 observed, 35.97 expected, observed/expected ratio (o/e) 1.14, 90% interval 0.89 to 1.48.